ENSG00000293164 (novel protein)
Gene: Protein-coding gene on chromosome 20 (32,186,477 to 32,190,360, reverse strand). Ensembl gene ENSG00000293164.
Gene Ontology:
Biological process: nucleosome assembly
Cellular component: chromatin; nucleus
Homologues: Orthologues: mouse Tspyl3 (65% identical), rat Tspy26 (64% identical), zebrafish tspy (27% identical), Drosophila melanogaster Set (22% identical), Caenorhabditis elegans spr-2 (19% identical), Drosophila melanogaster Nap1 (15% identical), zebrafish nap1l4a (14% identical), Drosophila melanogaster CG3708 (13% identical), Caenorhabditis elegans nap-1 (13% identical), Drosophila melanogaster mil (11% identical). Paralogues in human: TSPYL1 (53% identical), TSPYL4 (52% identical), TSPYL6 (52% identical), TSPYL2 (42% identical), TSPYL5 (40% identical), TSPY4 (25% identical), TSPY9 (25% identical), TSPY1 (25% identical), TSPY10 (25% identical), TSPY2 (25% identical), TSPY3 (25% identical), TSPY8 (25% identical), and 7 more.